FCRL3 (Fc receptor like 3)
Diseases named in the same sentence as FCRL3 in open-access papers (continued):
Sharing a sentence is not in itself a finding about the gene and the disease.
Autoimmunity (12 papers, 2008 to 2025). The occurrence of an immune reaction against the organism's own cells or tissues. "It has been noted that the FCRL3 gene confers a risk of allergic rhinitis (an autoimmune condition) in the Chinese population." (PMID 33889124, 2021). "The T allele increases FCRL3 transcription, which may promote immune dysregulation and susceptibility to autoimmunity." (PMID 41300769, 2025). "Structural changes arising from such variants may impair the normal function of FcRL3 and contribute to the immune dysregulation characteristic of autoimmunity." (PMID 41300769, 2025). "Among potential pathophysiological mechanisms, FCRL3 may predispose to clinical autoimmunity by pleiotropic regulation of the production of other deleterious autoantibodies." (PMID 28458671, 2017). "In other words, the Polymorphisms in FCRL3 could play an important autoimmunity role in AR pathogenesis by mediating functions of B/T Cells." (PMID 25594855, 2015). "Collectively, these mechanisms suggest that FcRL3 is a key regulator of inflammatory immune responses—helping to maintain immune homeostasis under normal conditions but contributing to autoimmunity when dysregulated." (PMID 41300769, 2025). "High surface expression of FcRL family members, including FcRL3, furthermore suggests a role for these cells in autoimmunity." (PMID 36281956, 2023). "FCRL3 (Fc receptor like 3 genes), a novel immunoregulatory gene, has recently been reported as a new promising candidate gene for general autoimmunity." (PMID 31341856, 2019). "Experimental inhibitors of these enzymes may therefore modulate FcRL3 activity, leading to reduced inflammation and attenuation of signals that promote autoimmunity." (PMID 41300769, 2025). "This hypothesis is supported by an overrepresentation of ITIMs in their cytoplasmic tails and numerous studies that have shown an association between autoimmune disorders and genetic variation in FCRL genes, more specifically the involvement of FCRL3 polymorphisms in autoimmunity." (PMID 33708190, 2020). "Outside of the HLA region, we discovered the association of several genes with autoantibody positivity, including evidence for association of the ABO blood gene with autoimmunity and also, surprisingly, a strong association of the known autoimmunity gene, FCRL3, with IA-2A, but not with T1D." (PMID 21829393, 2011).
autoimmune thyroid disease (9 papers, 2006 to 2024). Inflammatory disease of the thyroid gland due to autoimmune responses leading to lymphocytic infiltration of the gland. "For example, the rs7528684-G risk allele for Autoimmune thyroiditis, according to our eQTL data, increases the expression of the FCRL3 gene in several immune cells, which is also supported by prior evidence." (PMID 36400766, 2022). "The earliest GWAS studies on autoimmune thyroid disease showed association of GD with multiple loci within the HLA class I and II regions, and also in TSHR and FCRL3." (PMID 27863461, 2016). "In conclusion, our findings indicate that FCRL3 and FCRL4 expression levels are significantly increased in patients with GD and that this phenomenon is associated with hyperthyroidism but not with thyroid autoimmunity." (PMID 39274506, 2024).
endometriosis (7 papers, 2013 to 2020). The growth of functional endometrial tissue in anatomic sites outside the uterine body. "Further large-scale studies in the future are warranted to explore the association between FCRL3 genetic polymorphisms and endometriosis-related infertility, as well as other human diseases, in Asian and other ethnicities." (PMID 26334889, 2015). "The aim of the study was to investigate the association between FCRL3 genetic polymorphisms and the risk of endometriosis-related infertility in Han Chinese, and a further meta-analysis was conducted to confirm our results." (PMID 26334889, 2015). "The FCRL3 (rs7528684) SNP has also been demonstrated a significantly increased frequency of the C/C genotype in Polish women with endometriosis-associated infertility than controls." (PMID 25594855, 2015). "Recently, the FCRL3 −169T>C SNP was demonstrated as a risk factor of endometriosis related infertility." (PMID 23553198, 2013). "FCRL3 −169T>C polymorphism alters the expression of FCRL3 and can be a risk factor of endometriosis-related infertility." (PMID 23553198, 2013). "Recently, the FCRL3 −169T>C (rs7528684) single-nucleotide polymorphism (SNP) has been demonstrated to be a risk factor of endometriosis related infertility." (PMID 23553198, 2013). "We found a significantly increased frequency of the FCRL3 C/C genotype in women with endometriosis-associated infertility than controls [OR = 1.681 (95 % CI = 1.120–2.522, p = 0.0116, pcorr = 0.0348)]." (PMID 23553198, 2013). "We also found significantly increased FCRL3 transcript levels in the CD19+ B cells from carriers of the FCRL3 −169T C gene variant as compared with carriers of the FCRL3 −169 TT genotype both in women with endometriosis-related infertility and fertile women." (PMID 23553198, 2013). "Our study confirmed an association of the FCRL3 −169T>C polymorphism with endometriosis-related infertility." (PMID 23553198, 2013). "We found an approximately 1.4-fold significantly increased frequency of the FCRL3 C/C genotype in in women with infertility-associated endometriosis over the controls [OR = 1.681 (95 % CI = 1.120–2.522, p = 0.0116, pcorr = 0.0348)]." (PMID 23553198, 2013). "We observed an association of the FCRL3 −169T>C polymorphism with occurrence of endometriosis related infertility." (PMID 23553198, 2013). "Therefore, they were adjusted in the multivariable logistic regression models for analyses of the association between FCRL3 genetic polymorphisms and the risk of endometriosis-related infertility." (PMID 26334889, 2015). "It alters the expression of FCRL3 and can be a risk factor of endometriosis-related infertility." (PMID 25594855, 2015). "There were also significantly increased FCRL3 transcript levels in the CD19+ B cells from carriers of the FCRL3 −169 C gene variant as compared with carriers of the FCRL3 −169 TT genotype in women with endometriosis-related infertility." (PMID 23553198, 2013). "Therefore, we studied whether the FCRL3 −169T>C SNP may be associated with endometriosis-related infertility in a sample of the Polish population." (PMID 23553198, 2013). "The cumulative effect of interaction of FCRL3 –169T>C and FOXP3 –2383C>T polymorphisms has previously been demonstrated in the development of endometriosis." (PMID 30021560, 2018). "The median of FCRL3 transcript levels in B cells from endometriosis women with the CC genotype was 1.017 (range 0.493–2.120) (p = 0.012), with the CT genotype was 0.951 (range 0.406–2.616) (p = 0.015), and with the TT genotype was 0.485 (range 0.391–0.611)." (PMID 23553198, 2013). "Furthermore, the combination of FCRL3 and FOXP3 genotypes increases the risk of endometriosis, as observed in the Brazilian population samples." (PMID 32802844, 2020). "To date, the genetic risk factors for endometriosis-related infertility have also included the ESR1, ESR2, and luteinizing hormone beta-subunit FOXP, complement component 3, lysyl oxidase-like protein 4, and FCRL3 genes." (PMID 28405865, 2017).
endometriosis (continued). "According to the most recent studies, the following genes may account for the potential risk factors of infertility associated with endometriosis: ESR1, ESR2, beta hormone luteinizing gene, FOXP subunit, complement component 3 gene, and the Fc receptor-like 3 (FCRL3) gene." (PMID 33153202, 2020). "However, this linkage has not been studied in Chinese population and there has been no meta-analysis on the interrelationship of FCRL3 gene and endometriosis-related infertility." (PMID 26334889, 2015).
Infertility (7 papers, 2013 to 2023). "To date, the cause-and-effect relation underlying EM and infertility is still poorly elucidated, and several genes regulating inflammation and angiogenesis are currently being explored as potential etiologic factors; among them, FCRL3 is a promising candidate." (PMID 37626618, 2023). "In this light, an in-depth characterisation of the FCRL3 gene’s role in relation to infertility mechanisms could pave the way, in the future, for novel strategies for the better early clinical management of patients with infertility issues." (PMID 37626618, 2023). "Previous studies have shown that the increased levels of FCRL3-positive Tregs detected in EM patients could be responsible for a reduced immune response that could enable the implantation of endometrial cells and infertility onset." (PMID 37626618, 2023). "In contrast, the rs7528684 polymorphism of the Fc-receptor like-3 (FCRL3) gene, which is involved in the activation of the NF-kB/MAPK pathways, increases the risk of disease-induced infertility, irrespective of disease stage." (PMID 34445738, 2021).
multiple sclerosis (6 papers, 2015 to 2025). A progressive autoimmune disorder affecting the central nervous system resulting in demyelination. "This study aims to investigate the association of Fc receptor-like 3 (FCRL3) gene variants with multiple sclerosis (MS) and neuromyelitis optica spectrum disorder (NMOSD) in a Chinese population cohort." (PMID 40689332, 2025). "Whereas the genetic mutations of FCRL3 had been rarely studied in the association with risk of NMO, there were several studies suggesting the significant associations of FCRL3 polymorphisms with multiple sclerosis." (PMID 26402798, 2015). "Furthermore, the Fc receptor-like 3 (FCRL3) gene was previously found to be susceptible for a certain inflammatory demyelinating diseases (such as multiple sclerosis)." (PMID 26402798, 2015). "our research effectively utilizes this research paradigm, revealing the crucial role of FCRL3 in multiple sclerosis." (PMID 39076991, 2024).
Behcet disease (5 papers, 2008 to 2019). A chronic, relapsing, multisystemic vasculitis characterized by mucocutaneous lesions, as well as articular, vascular, ocular and central nervous system manifestations. "A large number of gene polymorphisms, including FCRL3 (Fc receptor-like 3) gene were identified significant associations with Behçet’s disease." (PMID 25594855, 2015). "Therefore, a larger patient population is needed to clarify the association of FCRL3 with Behcet’s disease in different HLA and sex status." (PMID 19050767, 2008).
tendinopathy (4 papers, 2018 to 2023). "Salles and co-workers found that athletes carrying the FCRL3 rs7528684 variant had a higher risk of developing tendinopathy (OR = 1.44; 95% CI = 1.02–2.04)." (PMID 37372343, 2023). "The FCRL3 –169T>C polymorphism was associated with increased tendinopathy risk, either considering all cases, only athletes with tendon pain or those who were away from training due to pain." (PMID 30021560, 2018). "After adjusting for confounding factors (age, years of practice in volleyball, gender and pain), evaluated in multivariate logistic regression models, FCRL3 –169C polymorphism was associated with a higher risk of tendinopathy." (PMID 30021560, 2018). "Athletes with tendinopathy showed a significant higher frequency of the variant allele FCRL3 –169C compared with the controls." (PMID 30021560, 2018). "After adjusting for confounding factors, the FCRL3 –169C allele increases the risk (approximate 2-fold) of developing tendinopathy among athletes who present pain or were away from training due pain." (PMID 30021560, 2018). "For competitive athletes with tendinopathy, the FCRL3 −169 T>C rs7528684 and the BMP4 rs2761884 polymorphism could be used." (PMID 34366884, 2021). "In present study, we found that FCRL3 -169C allele was associated with increased tendinopathy risk." (PMID 30021560, 2018). "Based on the results of this study and the previous ones, we propose a hypothesis for the role of FCRL3 –169T>C polymorphism in the tendinopathy development." (PMID 30021560, 2018). "The combined analysis of FCRL3 –169T>C and FOXP3 –2383C>T suggested a gene-gene interaction in the susceptibility to tendinopathy." (PMID 30021560, 2018). "The main aim of this study was to investigate the contribution of FCRL3 –169T>C and FOXP3 –2383C>T polymorphisms as risk factors for tendinopathy development in volleyball athletes, as well as their association with tendinopathy symptoms and sports activities." (PMID 30021560, 2018). "The combined variant genotypes, FCRL3 –169TC or –169CC and FOXP3 –2383CT or –2383TT, were associated with an increased risk of tendinopathy among athletes with tendon pain (OR = 2.24; 95% CI: 1.14–4.40 and OR = 2.60; 95% CI: 1.11–6.10)." (PMID 30021560, 2018). "The combined analysis of FCRL3 –169T>C and FOXP3 –2383C>T suggests a gene-gene interaction in the susceptibility to tendinopathy." (PMID 30021560, 2018). "As far as we know, the present study is the first study to focus on the possible contribution of the FCRL3 –169T>C and FOXP3 –2383C>T polymorphisms to the susceptibility to tendinopathy in elite athletes." (PMID 30021560, 2018). "Furthermore, gene variants of FOXP3, FCRL3, BMP4, and FGF3 and FGF10 as well as FGFR1 were analyzed in connection with tendinopathy in competitive athletes." (PMID 34366884, 2021). "We hypothesized that polymorphisms in FCRL3 and FOXP3 genes may influence the onset and/or the progression of tendinopathy." (PMID 30021560, 2018). "FCRL3 –169T>C and FOXP3 –2383C>T polymorphisms are located near elements that regulate respective genes expression, thus it was deemed relevant to evaluate these polymorphisms as risk factors for tendinopathy development in athletes." (PMID 30021560, 2018). "Furthermore, in present study the combined variant genotypes of FCRL3 –169T>C and FOXP3 –2383C>T were also associated with an increased risk for developing tendinopathy among athletes who presented tendon pain or were away from training due to pain." (PMID 30021560, 2018). "In this study, FCRL3 and FOXP3 polymorphisms and male gender were associated with a moderate risk (approximate 2-fold), whereas athlete older age and higher years of practice in volleyball were associated with a higher risk (approximate 8-fold) of tendinopathy." (PMID 30021560, 2018).
tendinopathy (continued). "Moreover, a combined analysis of the FCRL3 –169T>C and FOXP3 –2383C>T polymorphisms was performed to investigate if their interaction would increase the risk of developing of tendinopathy among athletes who present tendon pain or were away from training due pain." (PMID 30021560, 2018).
COVID-19 (3 papers, 2022 to 2023). A disease caused by infection with severe acute respiratory syndrome coronavirus 2. "The genetically-predicted protein levels of OAS1 (OR=0.440, 95%CI=0.315 to 0.615, P = 1.57 × 10−6), FCRL3 (OR=1.032, 95%CI=1.030 to 1.034, P = 2.40 × 10−191) and ICAM5 (OR=0.780, 95%CI=0.691 to 0.880, P = 5.74 × 10−6) showed MR association with COVID-19 severity using data from GENOMICC." (PMID 35772218, 2022). "MR and colocalization prioritized four protein targets, FCRL3, ICAM5, ENTPD5 and OAS1 that showed effect on COVID-19 severity in European ancestry." (PMID 35772218, 2022). "In addition, our study identified four additional protein targets, FCRL3, ICAM5, ENTPD5 and OAS1, that showed effect on COVID-19 severity in Europeans." (PMID 35772218, 2022).
diabetes (3 papers, 2012 to 2023). "The HLA and FCRL3 associations with ZnT8A in cases who have had diabetes for ≤2 years are of comparable strength to those who have had diabetes for ≥9 years." (PMID 22526605, 2012). "Interestingly, wild-type PTPN22 (rs2476601 c.1858CC) combined with FCRL3 rs7528684 NG_023241.1:g.4832CC was previously associated with higher HbA1c at diagnosis but lower HbA1c at the sixth and later months in patients with type 1 diabetes mellitus." (PMID 37315092, 2023). "In age-at-onset and diabetes duration adjusted models, RELA/11q13 and FCRL3/1q23 SNPs were associated with IA-2A positivity, LPP/3q28 SNPs were associated with GADA positivity, and IFIH1/2q24 was associated with positivity for autoantibodies related to autoimmune gastritis and thyroid disease." (PMID 36181724, 2022).
thyroid (3 papers, 2017 to 2024). "However, four genetic variants associated with thyroid phenotypes published in the GWAS catalog (rs3761959, rs7528684, rs505922, and rs3184504) were also associated in cis and trans with nine circulating protein abundances (BGAT, CHSTB, DC-SIGN, Desmoglein-2, DYR, FCRL3, GP1BA, MBL, and VCAM-1)." (PMID 32182948, 2020).
Arthritis (2 papers, 2020 to 2024). Inflammation of a joint. "We validated cis-meQTL effects at 3 loci implicated by CIT (cg21124310/ANKRD55, cg07522171/JAZF1, and cg17134153/FCRL3) in an independent cohort of 39 patients with early arthritis using pyrosequencing." (PMID 31945409, 2020).
gastric cancer (2 papers, 2012 to 2025). A primary or metastatic malignant neoplasm involving the stomach. "Among 20 shared core genes across disease stages, 13 genes (e.g., FCRL3,EFEMP1,ANKRD29,STOX2) were identified as unfavorable prognostic factors for gastric cancer." (PMID 41367615, 2025). "Furthermore, integrating immune infiltration analysis and key gene-clinical correlation results, we propose that in gastric cancer, FCRL3 may partially suppress tumor invasion and metastasis by reducing M2 macrophage infiltration, yet overall it still plays a role in promoting cancer progression." (PMID 41367615, 2025). "FCRL3, EFEMP1, ANKRD29, and STOX2 may serve as potential biomarkers for monitoring the transition from precancerous lesions to gastric cancer, offering insights into the mechanisms of gastric carcinogenesis and supporting early diagnosis and intervention strategies." (PMID 41367615, 2025). "Nine human RNAs were significantly upregulated in EBV-infected compared to EBV negative gastric cancers: FCER2, MS4A1 (CD20), PLUNC, TNFSF9, TRAF1, CXCL11, IFITM1, PPARG, and FCRL3.." (PMID 22929309, 2012).
malaria (2 papers, 2017 to 2018). Malaria is a serious and sometimes fatal disease caused by a parasite that commonly infects a certain type of mosquito which feeds on humans. "However, emerging data suggests that the array of inhibitory receptors expressed by atypical MBCs varies by disease; for example, malaria-associated atypical MBCs upregulate the expression of FCRL3 and FCRL5 rather than FCRL4." (PMID 28953967, 2017).
type 1 diabetes (2 papers, 2012 to 2023). "The most associated SNP, rs7522061, (p = 1.13 × 10−16) is located in exon 4 of the FCRL3 gene (Ensembl version 63) and is in LD with rs7528684 (r2 = 0.89 in British controls), which has previously been shown to be associated with IA-2A in type 1 diabetes cases." (PMID 22526605, 2012).
vitiligo (2 papers, 2021 to 2025). Generalized well circumscribed patches of leukoderma that are generally distributed over symmetric body locations and is due to autoimmune destruction of melanocytes. "In SMR analyses and colocalization analyses, we identified three shared genes associated with both vitiligo and RA, including: FCRL3, FADS1, and FADS2." (PMID 40468464, 2025). "The SMR analyses and colocalization analyses results suggest that FCRL3, FADS1, and FADS2 are shared genes associated with both vitiligo and RA." (PMID 40468464, 2025). "Additionally, we detected potential shared susceptibility genes between vitiligo and RA through SMR analyses, namely FCRL3, FADS1, and FADS3." (PMID 40468464, 2025). "Further, our results demonstrated an inverse relationship between vitiligo lesional duration and the level of persistent immune response, including some of the immune biomarkers associated with good therapeutic response such as CXCL10, FCRL3, and T cell receptor genes." (PMID 33815367, 2021). "The eQTL data of FCRL3, FADS1, and FADS2 were analyzed for colocalization with GWAS data for both vitiligo and RA." (PMID 40468464, 2025).